AR (androgen receptor)
Diseases named in the same sentence as AR in open-access papers (continued):
Sharing a sentence is not in itself a finding about the gene and the disease.
Obesity (continued). "Moreover, recently, an AR-driven oncogene, cell cycle-related kinase (CCRK), collaborated with obesity-induced pro-inflammatory signaling to promote NASH-related hepatocarcinogenesis." (PMID 34299031, 2021). "Despite the fact that AR exerts pro-inflammatory effects like PPARD and RXRA, it was much less associated with development of obesity and diabetes unlike PPARD and RXRA." (PMID 29065888, 2017). "In summary, our results conclude that infiltrating pre-adipocytes could promote PCa metastasis via modulation of the miR-301a/AR/TGF-β1/Smad/MMP9 signaling, which might explain the link of potential obesity influences on the PCa progression." (PMID 25940439, 2015). "Authors conclude that in adipocytes AR plays an inhibitory role in leptin production, but lack of androgens signalling in the adipocyte is not sufficient to promote obesity." (PMID 22235202, 2012). "Although many emerging pharmacological interventions have been studied, such as testosterone supplementation, selective androgen receptor modulators, myostatin inhibitors, and anti-obesity drugs, there are no approved drugs for the treatment of SO in the elderly." (PMID 35371597, 2022). "However, it must be considered that the specific effects of ADPN effects on AR signaling may vary depending on the changes in ADPN levels, as observed in both obesity and BC." (PMID 34066328, 2021). "Well-designed clinical trials with sufficient statistical power and adequate validation are also in urgent need to elucidate whether obesity and the consumption of unbalanced diets may alter the response to ADT or AR signaling inhibitors and contribute to the acquisition of CR." (PMID 35582011, 2021). "Male mice lacking AR develop obesity with increased lipogenesis in WAT and liver." (PMID 22235202, 2012).
melanoma (92 papers, 2008 to 2026). A malignant, usually aggressive tumor composed of atypical, neoplastic melanocytes. "In melanoma, AR activation has been linked to enhanced tumor invasiveness and impairment of critical immune cell functions, ultimately diminishing the efficacy of immune checkpoint therapies." (PMID 41179298, 2025). "Increased AR activity is also negatively associated with immune cell infiltration in patients with melanoma." (PMID 40940929, 2025). "Preclinical models also revealed in male mice that anti-tumor responses diminished to BRAF/MEKi, associated with elevated androgen receptor (AR) expression in tumors, which promotes melanoma cell proliferation, particularly in testosterone-rich environments." (PMID 40361336, 2025). "Taken together, our findings identify the androgen receptor as a diagnostic guidance in melanoma and support the repositioning of AR blockers in clinical management of patients." (PMID 39837817, 2025). "Recent studies have implicated AR signaling as a critical regulator of the tumor microenvironment (TME) in melanoma." (PMID 40940929, 2025). "AR-positive melanoma is linked to worse clinical outcomes, with androgen receptor signaling promoting tumor progression through the regulation of invasion and metastasis related pathways." (PMID 40564107, 2025). "Mechanisms underlying sex associated differences in the role of androgen receptor (AR) in melanoma are unclear." (PMID 38326303, 2024). "Although emerging studies have highlighted tumorigenic roles for the male sex hormone androgen and its receptor (AR) in melanoma, cellular and molecular mechanisms underlying these sex-associated discrepancies are poorly defined." (PMID 38326303, 2024). "In an orthotopic skin cancer model, AR loss in human dermal fibroblasts increased the tumorigenic potential of squamous cell carcinomas and melanoma cells." (PMID 39682229, 2024). "A previous report suggested an opposite role of AR in melanoma patient survival, i.e., higher AR was associated with worse survival." (PMID 36833272, 2023). "Nevertheless, our finding is significant, as this is one of the first studies to show an association of tumor AR level with overall survival in melanoma patients." (PMID 36833272, 2023). "While short-term exposure of melanoma cells to BRAF inhibitors induces a notable increase in AR expression, this induction alone is insufficient to cause resistance to BRAF inhibitors, as it resulted instead from sustained AR expression." (PMID 37838724, 2023). "MITF has been heavily implicated in melanoma progression, and AR-positive melanoma patients were shown to have worse prognosis because the AR promotes cell invasion through an MITF-AXL signaling axis." (PMID 33525365, 2021). "Underlying these events, we find that AR is essential in melanoma cells for anchoring the DNA repair proteins Ku70/Ku80 to RNA polymerase II (Pol II) and preventing RNA Pol II–associated DNA damage." (PMID 33112375, 2021). "AR loss has been shown to also be important in melanoma, where its downregulation lead to STING activation and dsDNA breaks as the AR anchors DNA repair the Ku70/80 proteins to RNA polymerase." (PMID 33525365, 2021). "Loss of AR activity in both melanoma cells and tumors is sufficient to cause massive chromosomal DNA breakage and leakage into the cytoplasm, with a stimulator of IFN genes (STING)–dependent inflammatory signaling cascade." (PMID 33112375, 2021). "Coimmunoprecipitation (co-IP) and proximity ligation assays (PLAs) with antibodies against AR and these proteins showed that they effectively associate in various melanoma cell lines." (PMID 33112375, 2021).
melanoma (continued). "A number of convergent mechanisms are likely to be implicated in the AR dependence of melanoma cells, as revealed by shRNA-mediated silencing of the gene, down-modulation by a CRISPRi approach, and pharmacological inhibition by AR inhibitors." (PMID 33112375, 2021). "In contrast to most literature data on melanoma, high AR protein expression levels were associated with increased overall survival (OS) and progression-free survival (PFS)." (PMID 32645881, 2020). "AR has been implicated previously in the melanoma gender bias, where men suffer more frequent and severe melanomas than females." (PMID 31116991, 2019). "Although recent studies suggest that differences in activity of the androgen receptor (AR) underlie the observed sex bias, little is known about AR activity in melanoma." (PMID 31116991, 2019). "Epidemiological studies consistently indicate that melanoma is more aggressive and associated with a worse prognosis in men, which may be influenced by differential AR signaling." (PMID 40940929, 2025). "Although AR has been implicated in promoting melanoma aggressiveness and metastasis, clinical data suggest its role may be highly context-dependent." (PMID 40940929, 2025). "Thus, the acquisition of BRAFi resistance in multiple melanoma cell lines is consistently linked with increased AR expression and activity." (PMID 37838724, 2023). "Thus, in a syngeneic mouse model, decreased tumorigenicity of melanoma cells with AR loss is associated with enhanced modulation of innate and acquired immunity." (PMID 33112375, 2021). "In melanoma samples of the TCGA database, there is a 4% AR gene mutation frequency." (PMID 33112375, 2021). "We previously showed that in dermal fibroblasts, as in melanoma cells, loss of AR activity by either gene silencing or pharmacological approaches results in cellular senescence together with a senescence-associated secretory phenotype that promotes tumorigenesis of neighboring cancer cells." (PMID 33112375, 2021). "Although Linc00673 induces AR in a ligand-independent manner, the association of AR to melanoma invasion may partially explain why male melanoma patients experience more metastasis and lower survival than the corresponding female patients." (PMID 33390809, 2021). "Together, our findings identify and delineate an androgen-/AR-regulated signaling axis that drives melanoma malignancy, reinforcing melanoma as a sex-associated cancer and highlighting new therapeutic opportunities for the clinical management of melanoma invasiveness." (PMID 38326303, 2024). "While molecular studies and mouse models have provided much interesting information, we are interested in investigating whether AR was differentially expressed in melanoma tumors from men and women, and whether the tumor AR levels are associated with patient overall survival (OS)." (PMID 36833272, 2023). "In preclinical models of bladder, colon, melanoma, and liver cancer, T cell–intrinsic AR signaling has been shown to promote CD8+ T-cell exhaustion in males, contributing to sex-based disparities in antitumor immunity." (PMID 41486951, 2026). "By contrast, it significantly increases after 4 h of co-colture with NK cells and results lower in the androgen-treated co-coltures, supporting the role for androgen/AR axis in the control of NK cell activity and melanoma aggressiveness." (PMID 39837817, 2025). "Expression of the androgen receptor (AR) correlates with a poor prognosis in cutaneous melanoma patients and its over-expression promotes invasion in melanoma cultured cells and in vivo." (PMID 39837817, 2025). "In melanoma, gene silencing or pharmacological inhibition of AR in melanoma cell lines suppresses proliferation and induces cellular senescence." (PMID 40940929, 2025). "An additional future perspective is the potential use of Selective Androgen Receptor Modulators (SARMs) in treating melanoma." (PMID 40940929, 2025).
melanoma (continued). "Genetic knockdown or pharmacologic inhibition of AR induces senescence and limits tumorigenesis in patient-derived specimens and melanoma cells from male and female patients." (PMID 39837817, 2025). "The sex-based disparities in melanoma outcomes further support the involvement of AR in disease progression." (PMID 40940929, 2025). "Sex differences: Men, who generally have higher AR activity, often exhibit more aggressive melanoma and poorer outcomes compared to women." (PMID 40940929, 2025). "In this process, AR-driven FUT4 signaling alters cell–cell adhesion by disrupting N-cadherin-catenin-based junctional complexes between melanoma cells, which impacts adherens junctions (AJs) and promotes cellular spread." (PMID 40940929, 2025). "This evidence supports the role of AR as a broadly relevant therapeutic target in melanoma, with potential utility beyond patient sex-based differences." (PMID 40564107, 2025). "This trial indicates that inhibiting AR can synergize with immunotherapy, leading to improved outcomes for subsets of melanoma patients who have shown resistance to conventional treatments." (PMID 40940929, 2025). "Nevertheless, there is a potential crosstalk between T and sun exposure because a fish melanoma model showed that UVB irradiation was able to rapidly up-regulate AR expression, consistent with UV-increased T levels in humans." (PMID 41228208, 2025). "In summary, these and other findings in our study indicate that AR blockade by antagonists or somatic knockdown improves the responsiveness of melanoma cells to MMPs inhibitors or immunotherapeutic agents." (PMID 39837817, 2025). "Sustained AR signaling promotes melanoma tumorigenesis and its ligand activation enhances the metastatic potential in melanoma cells and mouse model." (PMID 39837817, 2025). "The molecular impact of AR in liver cancer, kidney cancer, melanoma, and lung cancer is controversial." (PMID 41228208, 2025). "The androgen receptor is a critical regulator of melanoma aggressiveness, influencing metastasis, immune evasion, and therapy resistance." (PMID 40940929, 2025). "A comprehensive understanding of AR’s role in melanoma will enable the translation of these insights into tangible clinical benefit." (PMID 40940929, 2025). "Androgen signaling has been linked to worse cancer progression and therapy resistance, as seen in melanoma, where males exhibit impaired tumor control due to higher androgen receptor (AR) expression." (PMID 40361239, 2025). "In summary, pharmacologic blockade of AR or ADAM10 impairs melanoma-derived spheroid growth and inhibits the invasive phenotype induced by androgens in melanoma cells." (PMID 39837817, 2025). "We now report that melanoma cells derived from subcutaneous or lymph node metastasis express the wild-type human AR, as indicated by biochemical and genetic analyses." (PMID 39837817, 2025). "Recent studies demonstrate that androgen receptor (AR) activity contributes to resistance against immunotherapy in melanoma." (PMID 40564107, 2025). "AR signaling promotes tumor progression and impairs antitumor immune function in both male and female melanoma cells." (PMID 40564107, 2025). "Therapy resistance: AR signaling enables melanoma to evade targeted treatments such as BRAF/MEK inhibitors and diminishes the effectiveness of immune checkpoint blockade." (PMID 40940929, 2025). "We now report that ligand activation of the androgen receptor drives melanoma invasiveness and its escape from natural killer-mediated cytotoxic effect." (PMID 39837817, 2025). "Recent data implicate sex hormones, particularly the AR, in modulating the metastatic behavior of melanoma cells." (PMID 40940929, 2025). "Addressing these translational barriers will be essential for advancing AR-targeted strategies in melanoma." (PMID 40940929, 2025). "Higher AR expressions are associated with poorer survival in ESCC, whereas the role of AR in the survival of HNSCC and melanoma patients is inconsistent." (PMID 41228208, 2025).
melanoma (continued). "The integration of AR inhibitors into the therapeutic landscape for melanoma presents a promising strategy to complement existing treatments and potentially overcome resistance to chemotherapy, targeted therapy, and immunotherapy." (PMID 40940929, 2025). "In melanoma, AR seemed to be heavily involved in the regulation of the tumor microenvironment and immune responses." (PMID 41228208, 2025). "Although it has not traditionally been considered hormonally driven, recent evidence links androgen receptor (AR) signaling to important aspects of melanoma biology, including tumor growth, metastasis, immune evasion, and resistance to therapy." (PMID 40940929, 2025). "A critical evaluation of risk–benefit ratios, alongside the development of more selective tissue-targeted AR inhibitors, will be required before the widespread clinical use of AR inhibitors in melanoma can be justified." (PMID 40940929, 2025). "Although emerging studies support the pro-tumorigenic role of androgen/androgen receptor axis in melanoma, the molecular bases of such evidence are still under intense investigation." (PMID 39837817, 2025). "Few melanoma-focused clinical trials have tested AR inhibitors, and most are small early-phase studies." (PMID 40940929, 2025). "In contrast, androgen and androgen receptor signaling can drive melanoma invasiveness, promote immune evasion by suppressing NK cell-mediated cytotoxicity, and contribute to resistance against targeted therapies." (PMID 41237160, 2025). "When expressed at high levels, AR is mainly localized to the nucleus of melanoma cells, whereas it is predominantly distributed perinuclearly in low AR-expressing melanoma cell lines and primary melanocytes." (PMID 40940929, 2025). "This review provides a comprehensive overview of AR’s intricate role in melanoma, focusing on its molecular mechanisms, its impact on immune evasion and therapy resistance, and its potential clinical applications." (PMID 40940929, 2025). "Mechanistically, AR promotes melanoma progression by activating a pro-metastatic gene program, suppressing anti-tumor immune responses, and altering the tumor microenvironment." (PMID 40940929, 2025). "At last, melanoma cells depleted of the androgen receptor become more responsive to the most commonly used immunocheckpoint inhibitors, suggesting that the receptor dampens the immunotherapy efficacy." (PMID 39837817, 2025). "Metastasis (spread): AR activates genes that increase the invasiveness of melanoma cells, aiding their movement, survival, and spread to other organs." (PMID 40940929, 2025). "In this review, we explore the multifaceted role of AR in melanoma, with a focus on three major domains: metastasis, immunosuppression, and therapeutic resistance." (PMID 40940929, 2025). "For example, in a recent study, it was shown that patients with melanoma with high AR activity and treated with ICIs respond worse to the therapy compared with those patients with low AR activity." (PMID 40940929, 2025). "AR signaling is also gaining attention in melanoma, with growing evidence linking AR activity to metastasis and resistance to both immunotherapy and targeted therapy." (PMID 40564107, 2025). "As the FAK inhibitor, VS-6063, and the MEK-1 inhibitor, PD98059, impair the androgen-triggered motility in wound scratch assay, we concluded that the androgen/AR axis engages and activates the two effectors to drive melanoma cell locomotion." (PMID 39837817, 2025). "Further, AR signaling was reported to drive melanoma invasiveness through tumorigenic fucosylation or the MITF/AXL axis." (PMID 41228208, 2025). "AR is present at low levels in all primary melanocytes, but to varying degrees among melanoma cells." (PMID 40940929, 2025). "Control images captured from melanoma cells stained with FITC-conjugated anti AR antibodies and Texas red-coupled secondary antibody indicate the specificity of our approach." (PMID 39837817, 2025).